MMP2 (matrix metallopeptidase 2)
Diseases named in the same sentence as MMP2 in open-access papers (continued):
Sharing a sentence is not in itself a finding about the gene and the disease.
chronic hepatitis B (3 papers, 2010 to 2022). "In other words, MMP2 increased in chronic hepatitis B and C due to the proposed associated vitamin D deficiency in such patients." (PMID 27942306, 2010). "Serum MMP2 levels in patients with chronic hepatitis B were significantly decreased, which was positively correlated with serum levels of the soluble intercellular adhesion molecule D100." (PMID 35342754, 2022). "The objective of this study is to investigate the significance of CK-18 M30 and MMP-2 levels in clinical use in patients with chronic hepatitis B (CHB), as well as their sensitivity in determining cirrhotic patients." (PMID 24032040, 2013). "The objective of this study was to investigate the significance of CK-18 M30 and MMP-2 levels for clinical use in patients with chronic hepatitis B (CHB), as well as their sensitivity in determining cirrhotic patients." (PMID 24032040, 2013). "Taken together, this may explain the significant increase of MMP2 in chronic hepatitis B and C compared to bilharziasis and the controls group." (PMID 27942306, 2010).
chronic hepatitis C (3 papers, 2020 to 2026). "A recent study reported increased serum levels of MMP-2, -7, and -9 in patients with chronic hepatitis C, which correlated to the fibrosis stage for MMP-7." (PMID 34065048, 2021). "The mRNA and protein expression of several MMPs is modified during chronic hepatitis C: the gelatinases MMP-2 and -9 are enhanced, while the collagenases MMP-1 and -13 are downregulated." (PMID 34065048, 2021). "(2013) for chronic hepatitis C patients included variables such as hyaluronic acid, TGF-β1, α2-macroglobulin, Matrix Metalloproteinase (MMP)-2, apolipoprotein-A1, urea, MMP-1, alpha-fetoprotein, haptoglobin, red blood cell count, hemoglobin, and TIMP-1." (PMID 41551471, 2026). "Elevated levels of MMP-2 and -9 were reported in the serum and/or liver specimens of chronic hepatitis C patients, correlating with the fibrosis stage but not with the viral load." (PMID 34065048, 2021).
chronic myeloid leukaemia (3 papers, 2019 to 2021). "HAND2‐AS1 restoration resulted in reduced N‐cadherin, vimentin, MMP‐2 and MMP‐9 expression, which was consistent with a former study in which HAND2‐AS1 reduced MMP‐2 and MMP‐9 expressions in chronic myeloid leukaemia." (PMID 32314545, 2020). "In contrast, PIWIL1 expression downregulates MMP-2 and MMP-9 and inhibits the proliferation and migration ability of chronic myeloid leukemia cells." (PMID 31443431, 2019).
complication (3 papers, 2015 to 2024). Any disease or disorder that occurs during the course of, or because of, another disease, treatment, or procedure. "A number of studies have shown that the dysregulation of MMP-2 may contribute to the development of diabetic vascular complications." (PMID 35997390, 2022). "Levels of HbA1c, LDL, triglycerides, MMP-1, MMP-2, MMP-3, MMP-9, MMP-10, TIMP-1 and markers of LGI and ED were significantly higher in individuals with vascular complications compared to those without." (PMID 25848912, 2015).
congenital heart anomalies (3 papers, 2019 to 2025). "Indeed, the present study provides the first piece of evidence of elevated MMP-2 and MMP-9 in adolescents and adults with repaired congenital heart disease at risk of ascending aortopathy." (PMID 30655554, 2019). "The results of our study and those of related studies indicate that MMP-2, MMP-9, TIMP-1, and according to our findings, also TIMP-2, play a role in the etiopathogenesis of VSD and other congenital heart anomalies in humans." (PMID 39466144, 2025).
dental fluorosis (3 papers, 2017 to 2024). A condition that results from excessive fluoride ingestion during tooth development, resulting in tooth discoloration ranging from white streaks to brown stains and cracks or pits in the tooth enamel. "After adjusting for confounding factors, including urinary fluoride, maternal education level, and per capita annual household income, multivariate Logistic regression analysis showed that BALP, OC, MMP-2, MMP-9, and PTH were independently associated with the risk of dental fluorosis (P<0.05)." (PMID 39876909, 2024). "Here we show that MMP-2 rs2287074 SNP (G/A), but not rs243865, was associated with Brick tea type fluorosis in Tibetans and Kazaks, China." (PMID 28079131, 2017). "The aim of this study was to investigate the association between dental fluorosis occurrence in children and bone metabolism-related indicators, including bone-specific alkaline phosphatase (BALP), osteocalcin (OC), matrix metalloproteinase (MMP-2, MMP-9, MMP-20), and parathyroid hormone (PTH)." (PMID 39876909, 2024). "The urine fluoride levels, BALP, MMP-2, and MMP9 of the children in the fluorosis group were higher than fluoride-free group, and the mother's educational level, per capita annual household income, OC, and PTH were lower than fluoride-free group (P<0.05)." (PMID 39876909, 2024). "High BALP, MMP-2, MMP-9, low OC, and PTH are independent factors affecting the occurrence of dental fluorosis and are related to the extent of dental fluorosis." (PMID 39876909, 2024). "In summary, high BALP, MMP-2, MMP-9, and low OC, PTH are independent factors affecting the occurrence of dental fluorosis and are related to the urinary fluoride level and the extent of dental fluorosis." (PMID 39876909, 2024). "As the urinary fluoride level and the extent of dental fluorosis increased, there was a gradual elevation in serum BALP, MMP-2, and MMP-9 levels in children, while OC and PTH levels gradually decreased (P<0.05)." (PMID 39876909, 2024). "Based on Spearman correlation analysis, a positive correlation was identified between the urinary fluoride level, the extent of dental fluorosis, and indicators such as BALP, MMP-2, and MMP-9." (PMID 39876909, 2024).
diabetic neuropathy (3 papers, 2008 to 2021). A chronic, pathological complication associated with diabetes mellitus, where nerve damages are incurred due to diabetic microvascular injury involving small blood vessels that supply these nerves, resulting in peripheral and/or autonomic nerve dysfunction. "In experimental diabetic neuropathy, the involvement of MMP-2 and MMP-9 has also been implicated." (PMID 34631222, 2021). "Gelatinases MMP-9 and MMP-2 play a critical role in the pathogenesis of diabetic neuropathy and may serve as a potential treatment target." (PMID 34631222, 2021). "In this study, we hypothesized and have provided evidence that MMP-9 and MMP-2 in the dorsal root ganglion (DRG) and dorsal horn (DH) of the spinal cord may play an important role in the pathogenesis of diabetic neuropathy and associated DNP." (PMID 34631222, 2021). "We assessed the effects of minocycline on nerve conduction velocity and intraepidermal nerve fibre (IENF) deficits in diabetic neuropathy and investigated the effects of minocycline or MMP-2 on neurite outgrowth from primary cultures of dissociated adult rat sensory neurons." (PMID 25158309, 2014). "Our study reveals a critical role for gelatinase MMP-9 and MMP-2 in myelin abnormalities and neuropathic pain in rodents with STZ-induced diabetic neuropathy." (PMID 34631222, 2021). "In the present study we have targeted MMP-2 and MMP-9 overactivation in diabetic neuropathy using a known MMP-2 and MMP-9 inhibitor, minocycline with a non-selective COX inhibitor aspirin." (PMID 21593984, 2008).
dissection (3 papers, 2020 to 2025). The separation and isolation of tissues for surgical purposes, or for the analysis or study of their structures. "In comparison to the control group, the aortic dissection model group exhibited decreased expression of MMP-2 and NF-κB in PVAT, while TNF-α and RUNX1 expression increased." (PMID 38693222, 2024).
encephalitis (3 papers, 2019 to 2025). An acute inflammatory process affecting the brain parenchyma. "Animal models of viral encephalitis have shown associations between increased concentrations of MMP-2 and infected brain cells such as astrocytes, microglia, and endothelial cells." (PMID 30777092, 2019). "In JE in mice, MMP9 is vividly upregulated intrathecally simultaneously with the development of the histopathological features of encephalitis, accompanied by MMP2 and MMP7." (PMID 40003967, 2025). "Significant positive correlations were found between sCD146 levels and IL-10 (r=0.479, p=0.021), IL-6 (r=0.452, p=0.031), and MMP2 (r=0.415, p=0.049) in the CSF of anti-NMDAR encephalitis patients in the acute stage." (PMID 34220828, 2021).
hearing loss (3 papers, 2020 to 2026). "We hypothesize that aortic stiffness and aortic blood pressure will be associated with hearing loss and attenuated by inflammatory biomarkers [matrix metalloproteinase-2 (MMP-2), resistin, and vaspin]." (PMID 41756249, 2026). "Together, our data motivate further evaluation of the roles other MMPs, in particular MMP-2 and MMP-9, play in interacting with MMP-14 to promote VS growth and development of associated hearing loss in larger datasets." (PMID 32848608, 2020). "Additionally, MMP2, MMP9, and other ECM molecules contribute to cochlear tissue remodeling and blood–labyrinth barrier permeability in noise-induced hearing loss." (PMID 34206364, 2021).
hydronephrosis (3 papers, 2015 to 2022). Collection of urine in the renal pelvis that results in dilatation of the renal pelvis and calyces. "This study evaluates serum and urinary metalloproteinases MMP-1, MMP-2, and MMP-9 and tissue inhibitors of metalloproteinases TIMP-1 and TIMP-2 as potential biomarkers of ON in children with congenital unilateral hydronephrosis (HN) caused by UPJO." (PMID 32670438, 2020). "In conclusion, both homozygous and heterozygous genetic inactivation of Mmp2 protect mice against hydronephrosis and kidney fibrosis after UUO, as indicated by both histology and gene expression." (PMID 26673451, 2015). "UUO caused severe hydronephrosis in Mmp2+/+, which was accompanied by tubular dilation, necrosis and atrophy, while Mmp2-/- and Mmp2+/- showed considerably milder hydronephrosis, no tubular necrosis, and less tubular dilation." (PMID 26673451, 2015). "Urinary MMP-2, MMP-7, TIMP-2, and NGAL were measured as well as clinical characteristics including hydronephrosis grade, differential renal function, t1/2, and UPJO etiology." (PMID 35834547, 2022). "Damage was most severe in Mmp2+/+ mice, while both Mmp2-/- and Mmp2+/- groups showed considerably milder hydronephrosis, no tubular necrosis, and less tubular dilation." (PMID 26673451, 2015).
Hyperinsulinemia (3 papers, 2010 to 2020). An increased concentration of insulin in the blood. "Further, hyperinsulinemia contributes to for the instability of the atherosclerotic plaque: it increases the active forms of matrixmetalloproteinases (MMP)-2, MMP-9, and membrane type 1-MMP and the gelatinolytic activity of MMP-2." (PMID 21203503, 2010).
hypertrophic cardiomyopathy (3 papers, 2020 to 2023). A condition in which the myocardium is hypertrophied without an obvious cause. "Genes involved in hypertrophic cardiomyopathy such as Myh6 and Acta2, cardiac fibrosis such as Mmp2 and Col3a1, were all highly up-regulated by AB surgery, and hispidulin treatment significantly down-regulated these genes." (PMID 33324687, 2020).
intestinal tumour (3 papers, 2003 to 2013). "A number of different MMPs may be important in intestinal tumour formation as human tumours have been shown to express interstitial collagenase (MMP-1), gelatinase A (MMP-2), stromelysin 1 (MMP-3), matrilysin (MMP-7), gelatinase B (MMP-9), and stromelysin 3 (MMP-11)." (PMID 12778076, 2003).
kidney tumors (3 papers, 2016 to 2024). "Interestingly, the Broad-Novartis cancer cell line encyclopedia of gene expression analysis of renal tumor cell lines shows that 786–0 cells indeed have higher HDAC 1 gene expression as compared to the C2 cells, with a corresponding increase in MMP-2/9 gene expression." (PMID 27506904, 2016).
large cell lung cancer (3 papers, 2017 to 2020). "This study explored the mechanisms underlying MMP‐13 and MMP‐2 regulation of tumour VM formation in large cell lung cancer (LCLC)." (PMID 28766880, 2017).
malaria (3 papers, 2019 to 2021). Malaria is a serious and sometimes fatal disease caused by a parasite that commonly infects a certain type of mosquito which feeds on humans. "Local MMP2 upregulation has been seen in experimental cerebral malaria, a clinical subphenotype of severe malaria also linked to CD8+ T cell-mediated tissue injury, and MMP9 functional polymorphisms are thought to increase susceptibility to placental malaria." (PMID 33563839, 2021). "Placental malaria did not have any significant effect on MMP2 or MMP9 in this study." (PMID 31042729, 2019). "After adjusting for maternal age and malaria status, HIV-1 status had no significant impact on MMP2, MMP9 and Gal-13 (all p>0.05)." (PMID 31042729, 2019).
melasma (3 papers, 2016 to 2024). "Basement membrane disruption caused by elevated levels of MMP-2 and MMP-9 facilitates the descent of melanocytes into dermis, which makes the treatment of melasma challenging." (PMID 27240341, 2016). "Interestingly, the rise in MMP-2 and reduction in collagen type IV, which is the major component of the epidermal basement membrane, correlated with the increase in the number of melanocytes that protruded into the dermis in melasma." (PMID 34299100, 2021). "Prolonged UV exposure can induce matrix metalloproteinase-2 (MMP-2) and MMP-9 activation in basement membrane which can lead to collagen types 4 and 6 degradation and accumulation of more elastic fibers in melasma patients." (PMID 38628650, 2024).
mitral valve disease (3 papers, 2015 to 2024). "The aim of this study is to investigate the link between genetic variants in MMP2 and mitral valve prolapse, including mostly severe cases with mitral repair by surgery and Barlow, myxomatous disease." (PMID 29371517, 2015). "Association of MMP2 common tagSNPs with mitral valve prolapse." (PMID 29371517, 2015). "Association of MMP2 common tagSNPs with myxomatous (Barlow disease) and non-myxomatous mitral valve prolapse." (PMID 29371517, 2015). "Mutations in a variety of genes that are responsible for encoding structural proteins, signaling molecules, and transcription factors—namely FBN1, FLNA, MMP2, and SOX9—have been identified as significant contributors to the pathology of mitral valve diseases." (PMID 39273357, 2024).
morbid obesity (3 papers, 2015 to 2024). An excess of body weight, normally defined as an individual with a body mass index greater than 35 or a body weight greater than one hundred percent of ideal body weight. "Medians of CD40L, adiponectin, MMP-2, MMP-9, and PAI-1 levels were higher in the group of morbid obesity patients as compared to the control group." (PMID 25261984, 2015).
mucositis (3 papers, 2019 to 2025). Mucositis is inflammation and damage of the mucous membranes lining the mouth and other parts of the gastrointestinal (GI) tract. "MMP-1, MMP-2, MMP-8, and TIMP-1 activities in serum, stomach, small intestine, and large intestine were significantly higher in the Mucositis group in comparison to the Control and ALA groups (p < 0.05–0.0001)." (PMID 36290656, 2022). "In comparison to the Control and ALA groups, 5-FU treatment enhanced MMP-1, MMP-2, MMP-8, and TIMP-1 activation in sera and tissues in the Mucositis + ALA group." (PMID 36290656, 2022). "The aim of this study was to evaluate the levels of salivary biomarkers IL-1β, IL-10, RANK, OPG, MMP-2, TG-β and TNF-α in individuals with diagnosis of peri-implant mucositis in the absence or presence of periodontal and peri-implant maintenance therapy (TMPP) over 5 years." (PMID 30810638, 2019).
nephritis (3 papers, 2009 to 2021). Inflammation of renal tissue. "BW mice were sacrificed approximately every second week (in sets of 3) until development of end-stage lupus-like nephritis, and were analyzed for renal Dnase1, MMP2 and MMP9 mRNA levels and for corresponding enzyme activities." (PMID 20041189, 2009). "For each parameter, it was difficult to determine correlation between e.g. Dnase1, MMP2 or MMP9 mRNA levels with age in individual mice since nephritis developed at different time points in different mice." (PMID 20041189, 2009). "Since nephritis does not appear at the same age in individual BW mice, instead of relating data to age, levels of Dnase1, MMP2 and MMP9 mRNA were combined for each mouse, and this set of data was sorted by descending Dnase1 mRNA levels." (PMID 20041189, 2009).
nephrotic syndrome (3 papers, 2019 to 2023). A collection of symptoms that include severe edema, proteinuria, and hypoalbuminemia; it is indicative of renal dysfunction. "MMP2 and MMP9 were found significantly elevated in the urine of patients with steroid-resistant nephrotic syndrome as compared to steroid-sensitive patients." (PMID 30921378, 2019).
non-alcoholic fatty liver disease (3 papers, 2023 to 2024). "Nonalcoholic fatty liver disease (NAFLD), often present in the obese patients, is associated with increased serum concentrations of MMP-2, MMP-9, TIMP-1, 2, TGF-beta concentrations." (PMID 38541059, 2024).
osteonecrosis (3 papers, 2015 to 2026). A none disease characterized by death of bone tissue due to a lack of blood supply. "MMP-9 predicted future osteonecrosis with higher sensitivity and specificity (area under the receiver operating characteristic curve [AUC] 0.84 [95% CI 0.84–0.99]; sensitivity/specificity 82%/75%; cutoff value ≤ 72,420 pg/mL) than osteopontin, MMP-2 and VEGF-C when taken alone." (PMID 39590837, 2024). "MMPs levels were differently expressed in patients with osteonecrosis (elevated MMP-2 and decreased MMP-9) when compared with those free from osteonecrosis." (PMID 39590837, 2024). "Patients with osteonecrosis showed increased osteopontin and matrix metalloproteinase (MMP)-2 levels and decreased MMP-9 and vascular endothelial growth factor (VEGF)-C compared with those free from osteonecrosis." (PMID 39590837, 2024).
ovarian endometriosis (3 papers, 2014 to 2019). A non-neoplastic disorder characterized by the growth of endometrial tissue in the ovaries. "In conclusion, ovarian endometriosis is associated with increased MMP-2 activity and pathological angiogenesis." (PMID 27695098, 2016). "The present study aims to understand the regulation of MMP-2 activity in endothelial cells and on angiogenesis during progression of ovarian endometriosis." (PMID 27695098, 2016). "The present study has evaluated the angiogenic role of MMP-2 activity in ovarian endometriosis patients and looked into the signaling responses to PGE2, using in vivo and in vitro studies." (PMID 27695098, 2016). "However, in ectopic ovarian endometriosis, increased MMP-2 activities were observed with the disease progression, suggesting its involvement in the pathogenesis through aberrant cellular remodeling." (PMID 27695098, 2016). "However, unlike serum, both pro and active forms of MMP-2 were present in ectopic samples of ovarian endometriosis." (PMID 27695098, 2016).
pituitary tumor (3 papers, 2016 to 2025). A benign or malignant neoplasm affecting the pituitary gland. "Given the established association between pituitary tumors and elevated levels of MMP-9—and, to a lesser extent, MMP-2—there is potential for further research to develop radiolabels targeting these specific molecules." (PMID 41206839, 2025). "They then performed IHC only for MMP-2 and -14 and confirmed increased levels of these two proteins in invasive pituitary tumors." (PMID 31640258, 2019). "In a study that included 54 pituitary tumors, it was reported that invasive pituitary tumors expressed increased levels of MMP-2 and MMP-9 mRNA and protein compared to non-invasive tumors." (PMID 31640258, 2019). "In 2006, Malik and Kakar found that pituitary tumor transforming gene facilitated tumor growth and metastasis through secretion of MMP-2 in vitro." (PMID 27310993, 2016).